GABRB3 (gamma-aminobutyric acid type A receptor subunit beta3)
Description:
Beta subunit of the heteropentameric ligand-gated chloride channel gated by gamma-aminobutyric acid (GABA), a major inhibitory neurotransmitter in the brain. GABA-gated chloride channels, also named GABA(A) receptors (GABAAR), consist of five subunits arranged around a central pore and contain GABA active binding site(s) located at the alpha and beta subunit interface(s). GABAARs containing beta-3/GABRB3 subunit are found at both synaptic and extrasynaptic sites (By similarity). When activated by GABA, GABAARs selectively allow the flow of chloride anions across the cell membrane down their electrochemical gradient. Chloride influx into the postsynaptic neuron following GABAAR opening decreases the neuron ability to generate a new action potential, thereby reducing nerve transmission. GABAARs containing alpha-1 and beta-3 subunits exhibit synaptogenic activity; the gamma-2 subunit being necessary but not sufficient to induce rapid synaptic contacts formation. Extrasynaptic beta-3 receptors contribute to the tonic GABAergic inhibition (By similarity). GABAARs containing alpha-1, beta-3 and epsilon subunits may also permit spontaneous chloride channel activity while preserving the structural information required for GABA-gated openings (By similarity). Beta-containing GABAARs can simultaneously bind GABA and histamine where histamine binds at the interface of two neighboring beta subunits, which may be involved in the regulation of sleep and wakefulness. Plays an important role in somatosensation and in the production of antinociception (By similarity).
Synonyms: DEE43; ECA5; EIEE43
Tractability: Small molecule: an approved drug acts on it; a structure with a bound ligand is known; a high-quality ligand is known; it belongs to a druggable protein family. Antibody: UniProt places it where antibodies can reach, with high confidence; its Gene Ontology location is reachable by antibodies, with high confidence; UniProt predicts a signal peptide or a membrane-spanning region. PROTAC: ubiquitination databases record sites on it; its protein half-life has been measured; a small molecule that binds it is known.
Target class: Ion channel; GABA-A receptor; Ligand-gated ion channel
Safety:
Unwanted effects reported when the protein is acted on. In parentheses: how it was acted on, where the effect was seen, and who reports it.
opioid dependence (source: ClinPGx)
Gene: Protein-coding gene on chromosome 15 (26,543,552 to 26,939,539, reverse strand). Ensembl gene ENSG00000166206.
Subcellular location: Postsynaptic cell membrane; Cell membrane; Cytoplasmic vesicle membrane
Pathways (Reactome):
Neuronal System: GABA receptor activation
Signal Transduction: Signaling by ERBB4
Gene Ontology:
Molecular function: GABA-A receptor activity; GABA-gated chloride ion channel activity; identical protein binding; chloride channel activity; extracellular ligand-gated monoatomic ion channel activity; monoatomic ion channel activity; signaling receptor binding; transmembrane signaling receptor activity; transmitter-gated monoatomic ion channel activity involved in regulation of postsynaptic membrane potential
Biological process: cellular response to histamine; chloride transmembrane transport; gamma-aminobutyric acid signaling pathway; inhibitory synapse assembly; synaptic transmission, GABAergic; extrasynaptic signaling via GABA; negative regulation of synaptic transmission, GABAergic; roof of mouth development; signal transduction; chemical synaptic transmission; cochlea development; genomic imprinting; inhibitory postsynaptic potential; inner ear receptor cell development; innervation; monoatomic ion transmembrane transport; monoatomic ion transport; neuron development
Cellular component: chloride channel complex; dendritic spine; GABA-A receptor complex; plasma membrane; postsynaptic membrane; cytoplasmic vesicle membrane; GABA-ergic synapse; postsynaptic specialization membrane; cell surface; membrane; synapse
Genetic constraint (gnomAD): Loss-of-function variants: 14 observed, 49.91 expected, observed/expected ratio (o/e) 0.28, 90% interval 0.18 to 0.44. The upper end of that interval is the gene's LOEUF score, 0.44, which puts it in group 1 of 6, group 1 being the genes least tolerant of losing a copy. Missense variants: 307 observed, 608.38 expected, observed/expected ratio (o/e) 0.5, 90% interval 0.46 to 0.56. Synonymous variants: 260 observed, 230.02 expected, observed/expected ratio (o/e) 1.13, 90% interval 1.02 to 1.25.
Gene-disease validity (ClinGen):
ClinGen rates the evidence that GABRB3 causes each of these diseases.
genetic developmental and epileptic encephalopathy (autosomal dominant): Definitive. A complex neurodevelopmental disorder characterized by a range of developmental delays and epileptic encephalopathy phenotypes.
Homologues: Orthologues: macaque GABRB3 (99% identical), mouse Gabrb3 (97% identical), rat Gabrb3 (97% identical), chimpanzee GABRB3 (95% identical), dog GABRB3 (93% identical), rabbit GABRB3 (93% identical), pig GABRB3 (92% identical), tropical clawed frog gabrb3 (88% identical), guinea pig GABRB3 (83% identical), zebrafish gabrb3 (83% identical). Paralogues in human: GABRB2 (78% identical), GABRB1 (76% identical), GABRQ (42% identical), GABRR1 (37% identical), GABRD (37% identical), GABRR2 (37% identical), GABRP (37% identical), GLRA3 (36% identical), GABRR3 (36% identical), GLRA1 (36% identical), GLRA2 (36% identical), GABRA4 (34% identical), and 33 more.
Diseases named in the same sentence as GABRB3 in open-access papers:
GABRB3 is named in the same sentence as 112 diseases in open-access papers, as found by Europe PMC text mining. Sharing a sentence is not in itself a finding about the gene and the disease. The quoted sentences say what the papers report.
epilepsy (50 papers, 2013 to 2025). A brain disorder characterized by episodes of abnormally increased neuronal discharge resulting in transient episodes of sensory or motor neurological dysfunction, or psychic dysfunction. "While several rodent models (e.g., Scn1a, Scn2a, and Gabrb3 mutants) represent specific genetic mutations associated with epilepsy, others such as GAERS or WAG/Rij rats display spontaneous spike–wave discharges typical of GGEs." (PMID 41585885, 2025). "GABRB3 is an important neurodevelopmental gene that has been extensively studied in epilepsy and is largely associated with various brain dysplasia." (PMID 37685269, 2023). "In this study, we address these two conundrums: Firstly, we interrogated the GABAergic function of epilepsy-associated GABRB3 variants from a total of 85 patients." (PMID 35383156, 2022). "The differential pathomechanisms in GABRB3 mutations associated with epilepsy with variable severities have been identified." (PMID 36077081, 2022). "In our previous study of other types of GABAA receptor-related epilepsy, we found that patients with GABRB2 and GABRB3 variant-related epilepsy patients also had a good response to valproate and levetiracetam." (PMID 35359574, 2022). "GABRB3 variants that cause epilepsy have emerged at a steady rate in recent years, however, in most cases variants have been reported without any analysis of their functional effects." (PMID 35383156, 2022). "The spectrum of epilepsy syndromes was strikingly diverse in patients with GABRB3 variants, showing a wide range of age of seizure onset between 0 and 14 years of age and different seizure types." (PMID 35383156, 2022). "Although a mutation in the GABRB3 gene was associated with a 3–6 times greater risk of ASD with epilepsy, the mutation of other GABAAR subunits, including the β1 and α4 subunits, has also been coupled with ASD within various ethnic groups." (PMID 33535681, 2021). "A number of studies have demonstrated that GABRB3 gene mutations are associated with a broad phenotypic spectrum of epilepsies, and that reduced GABAAR function, causing GABAAergic disinhibition, represents the relevant disease mechanism." (PMID 33535681, 2021). "Mutations in GABRB3 have been identified in subjects with different types of epilepsy and epileptic syndromes, including West syndrome (WS), Dravet syndrome (DS), Lennox‐Gastaut syndrome (LGS), myoclonic‐atonic epilepsy (MAE), and others." (PMID 32945607, 2020). "In addition, it has been demonstrated that epilepsy-associated pathogenic GABRB3 Tyr302Cys (Y302C) variants can lead to loss-of-function receptors, and patients with this variant have severe developmental and epileptic encephalopathies." (PMID 40738983, 2025). "GABRB3 mutation is associated with epilepsy and autism, highlighting a function in embryonic development that could implicate its role in developing neuroblasts." (PMID 38398114, 2024). "We identified 54 epilepsy-associated missense variants within the coding region of GABRB3." (PMID 35383156, 2022). "One should notice that genes such as CHRNA7 and GABRB3 are located within larger deletions containing other genes; so they might be questionable as bona fide epilepsy-associated genes." (PMID 30148849, 2018). "Similarly, Y277C mutation in GABRB2 or GABRB3 lead to epilepsy (74, –76)." (PMID 41129221, 2025). "Therefore, we speculate that GABRB3 gene mutations in epilepsy patients might affect lipid metabolism." (PMID 33287870, 2020). "Mutations in other epilepsy related genes, such as GABRG2, GABRB3, CACNA1H, and GABRA1, have been implicated in childhood absence epilepsy (CAE)." (PMID 41585885, 2025). "The first reports of epilepsy‐associated de novo variants included variants within the GABAA receptor subunit encoding genes, GABRA1 and GABRB3." (PMID 37621067, 2024). "FS are relatively common in GABAA receptor‐associated epilepsies caused by variants in GABRA1, GABRB3 or GABRG2." (PMID 37621067, 2024).
epilepsy (continued). "This expands the clinical phenotype spectrum of GABRG2 mutations in epilepsy and further strengthens the notion of overlapping clinical phenotypes between GABRG2, GABRB3, and possibly other GABR mutations." (PMID 36077081, 2022). "The currently known epilepsy-associated variants identified in GABAA receptor subunits are predominantly distributed in the four genes (GABRA1, GABRB2, GABRB3 and GABRG2) that code for the most commonly distributed receptor isoforms." (PMID 34095830, 2021). "GABRB3 (gamma-aminobutyric acid receptor, Beta-3): Among 22 cases of epilepsy/EE (with mean onset at 8.7 months), one patient experienced neonatal-onset EE." (PMID 33919646, 2021). "It is well known that mutations/variants in GABRA1, GABRB2, GABRB3, or GABRG2 produce several different types of epilepsy." (PMID 34095830, 2021). "Missense or nonsense mutations of GABRA1, GABRB3 and GABRG2 epilepsy genes are linked with classical GEs with autosomal dominant inheritance including, GEFS+, childhood absence epilepsy, febrile seizures, and juvenile myoclonic epilepsy." (PMID 27622563, 2016). "At present, there are too few reported cases of GABRB3‐related epilepsy for clear phenotype–genotype correlations or comparisons with Angelman syndrome due to chromosome deletions with GABRB3 haploinsufficiency." (PMID 26645412, 2016). "Mutations in several GABAAR subunit‐encoding genes, including the synaptic subunits GABRA1, GABRB3, and GABRG2 that associate with gephyrin, have been identified in epilepsy syndromes of different degrees of severity." (PMID 26613940, 2015). "Altered GABRB3 expression or function has been associated with ASD and epilepsy, suggesting that disruptions in GABAergic signaling may underlie the excitatory‐inhibitory imbalance observed in ASD." (PMID 40330750, 2025). "Several monogenic epilepsies may result from mutations in the GABRA1, GABRB3, and GABRG2 genes encoding for the predominant α1β3γ2 GABAA isoforms." (PMID 38003469, 2023). "We found that variants in the epilepsy-associated genes GABRA1, GABRB3 and GABRG2 were mainly present in the ESP variants, but the GEC cohort contained epilepsy-associated GABRA6, GABRB1, and GABRB2 and non-epilepsy- associated GABRA4, GABRA5, and GABRG3 genes." (PMID 27622563, 2016). "Among these, GRIN2A, GABRB3, and GRIN2D have been reported previously, supporting their roles in epilepsy pathophysiology." (PMID 40313715, 2025). "These CNVs contained or partially contained epilepsy-related genes, such as PRRT2 (16p11.2), ZBTB18 (1q43q44), and GABRB3 (15q11.2q13.1)." (PMID 39906551, 2024). "There are three neurological disorders, Rett syndrome, Angelman syndrome, and autism, which show lower GABRB3 and UBE3A gene expression, along with the manifestation of clinical phenotypes like intellectual disability and epilepsy." (PMID 38248358, 2023). "Gamma-aminobutyric acid receptor subunit beta-3 (GABRB3) is involved in pathogenesis of some diseases such as Angelman syndrome, Prader-Willi syndrome, epilepsy, and autism." (PMID 33712060, 2021). "Monogenic epilepsies can be characterized according to the gene function affected: Impaired function of ion channels (e.g., CACNA1A), receptors (e.g., GABRB3), transporters (e.g., SLC2A1), synapse-related (e.g., PRRT2), and other pathways (e.g., CDKL5, PCDH19) are associated with epilepsy." (PMID 38125836, 2023). "GABRA1, along with GABRB3, is vital for the formation of GABAA receptors and plays a pivotal role in GABAergic signaling that protects neurons in the brain from over-signaling, which can often lead to diseases such as epilepsy." (PMID 33816350, 2021).
epilepsy (continued). "Furthermore, genes such as SCN3B, EPHA4, GABRB3, and SCN2A may play roles in the development of epilepsy in the context of AD." (PMID 38999445, 2024). "For the deletion group, the GABRB3 maps to the region of 15q involved in AS could partially explain the deletion patients having worse epilepsy than other patients in the non-deletion group." (PMID 36011358, 2022).
autism (37 papers, 2005 to 2024). Persistent deficits in social interaction and communication and interaction as well as a markedly restricted repertoire of activity and interest as well as repetitive patterns of behavior. "Sex differences in basal cerebellar synaptic physiology have been described in weanling mice, and the response to an autism-linked mutation in Gabrb3 differs between the sexes." (PMID 39583831, 2024). "It has been reported that the GABRB3 gene polymorphism was significantly associated with autism among Iraqi patients." (PMID 33712060, 2021). "The cerebellum expresses several autism-linked genes, including GABRB3, which encodes GABAA receptor β3 subunits and is among the maternal alleles deleted in Angelman syndrome." (PMID 27077953, 2016). "GABRB3 has also been implicated in other neurodevelopmental disorders such as autism, childhood absence epilepsy, and Angelman syndrome." (PMID 26645412, 2016). "Missense mutations of GABRB3 have been reported to be associated with childhood absence epilepsy (P11S, S15F, G32R), insomnia (R192H), and autism (P11S)." (PMID 24999380, 2014). "Dysfunction of GABRB3 is highly associated with both epilepsy and autism symptoms." (PMID 29340132, 2018). "Moreover, 7 SNPs (rs3812922 in NIPA2, rs8037745 in SNRPN, rs4906771 and rs1345098 in ATP10A, rs12438141, rs1863467, and rs4906902 in GABRB3) displayed nominal association with autism under the additive model in our samples (p < 0.05)." (PMID 30108208, 2018). "Although speculative, it is interesting to consider that autistic disorders might be linked to the maintenance of parent-of-origin allelic expression of GABRB3, as a result of failure to erase the fetal imprint." (PMID 21545704, 2011). "In mice, sevoflurane exposure induced autism-like behaviours and led to the downregulation of high-risk autism genes, including ARID1B, GABRA5, GABRB3, GRIN2B, SHANK3 and SUV420H1." (PMID 39372140, 2024). "15q11–q13 site contains coding regions of specific subunits of GABA-AR, including GABRB3, GABRA5, and GABRG3, which are strongly implicated in the pathogenesis of autism." (PMID 35198562, 2021). "Even the GABRB3 gene that is distal to the ATP10A gene is a SFARI (SFARI.org) recognized autism gene (Malacards.org; SFARI.org)." (PMID 32384786, 2020). "Nine SNPs (rs8025849 in NIPA1, rs3812922 in NIPA2, rs1009153 and rs2289818 in CYFIP1, rs8037745 in SNRPN, rs12438141 and rs1863467 in GABRB3, rs7403021 and rs7180500 in GABRG3) were nominally associated with autism under the recessive model (p < 0.05)." (PMID 30108208, 2018). "Other family-based studies detected nominally associated SNPs in GABRB3 and GABRA5 with autism in Europeans and Koreans20–22." (PMID 30108208, 2018). "GABRB3, which encodes the β3 subunit of the GABAA receptor (GABAAR), is an autism-linked gene with cerebellar expression." (PMID 27077953, 2016). "For examples, Shao and colleagues reported increased linkage of GABRB3 locus with autism in families sharing the high insistence-on-sameness scores." (PMID 24999380, 2014). "McCauley and colleagues conducted a LD analysis of genetic markers spanning the 1-Mb of 15q12; they found six markers across GABRB3 and GABRA5 nominally associated with autism." (PMID 24999380, 2014). "Cook and colleagues first reported linkage disequilibrium (LD) between autism and a genetic marker at GABRB3." (PMID 24999380, 2014). "Nevertheless, our findings are different from several postmortem studies that showed reduced GABRB3 expression in the brains of patients with autism." (PMID 24999380, 2014). "Our data are also compatible with the increased Gabrb3 expression seen in the chromosomal-engineered mouse model for human 15q11-13 duplication of autism." (PMID 24999380, 2014). "Investigating the interaction between the markers in four GABAA receptor subunit genes in an Argentinean sample of ASD, Sesarini and colleagues found that the genetic interaction between GABRB3 and GABRD was associated with an increased risk of autism." (PMID 24999380, 2014).